GIP (gastric inhibitory polypeptide)
Diseases named in the same sentence as GIP in open-access papers (continued):
Sharing a sentence is not in itself a finding about the gene and the disease.
Glucose intolerance (24 papers, 2008 to 2026). Glucose intolerance (GI) can be defined as dysglycemia that comprises both prediabetes and diabetes. "Nonetheless, although mice with GIPR signal inhibition in the PNS do not show alterations in body weight and remain fully sensitive to weight loss induced by GIPR antagonism, these mice develop glucose intolerance with impaired glucose-induced secretion of insulin and GIP when fed a HFD." (PMID 40301583, 2025). "Taken together, these findings strongly suggest that selective activation of Gs signaling in K cells stimulates the secretion of GIP and insulin when blood glucose levels are elevated, thus reversing the glucose intolerance characteristic of obese mice." (PMID 39436694, 2024). "There was no clear differences in the background data in studies reporting glucose intolerance or normal glucose tolerance in GIP or GLP-1 receptor KO mice, although a trend of a more severe glucose intolerance was reported at higher glucose loads." (PMID 34122340, 2021). "In contrast, in the studies using a lower glucose load of 1 or 1.5 mg/g, four out of eight study arms (i.e., 50%) showed glucose intolerance in GIP or GLP-1 receptor KO mice." (PMID 34122340, 2021). "Glucose intolerance and the fatty liver phenotype in PLB4 mice were further associated with drastically elevated levels of serum GIP." (PMID 27138913, 2016). "Polyphenolic ingredients regulated at blood sugar level after meals and improved glucose intolerance by facilitating insulin response and reducing the secretion of hormones such as glucose-dependent insulinotropic polypeptide (GIP) and glucagon-like polypeptide-1 (GLP-1)." (PMID 37521997, 2023). "GIP was associated with insulin secretion rates irrespective of glucose intolerance status." (PMID 28690913, 2017). "Retratrutide (LY3437943), a novel triple GLP-1, GIP, and glucagon receptor agonist, has a greater insulinotropic effect from both GIP and GLP-1 receptors than the glucose intolerance induced by the glucagon receptor." (PMID 39061960, 2024). "In this view, the increased GIP levels deserve attention too, as they are able to stimulate glucagon secretion; such effect may help to stabilize glucose levels in healthy individuals, whilst in T2D and obese subjects these may contribute to glucose intolerance." (PMID 30451975, 2019). "The coffee phenols, anthocyanin, and curcumin can regulate postprandial glycemia and decrease the progression of glucose intolerance by a simplified insulin response and improved secretion of glucagon-like polypeptide-1 (GLP-1) and glucose-dependent insulinotropic polypeptide (GIP)." (PMID 36557912, 2022). "The results were not straightforward, since glucose intolerance in GIP or GLP-1 receptor KO mice were reported only in eight of the arms, whereas normal glucose tolerance was reported in five arms." (PMID 34122340, 2021). "This is similar as our previous results in DIRKO mice, which have both GIP and GLP-1 receptor gene deletion, whichs suggests that GIP rather than GLP-1 explains the glucose intolerance after high oral glucose loads in DIRKO mice." (PMID 34122340, 2021). "In effect, pre-meal moderate-intensity exercise exacerbates evening glucose intolerance regardless of the dietary composition of the meals and without an effect on the dietary influence over evening postprandial insulin, GIP, and HOMA-IR." (PMID 27798656, 2016). "We have not observed changes in the level of glucose-dependent insulinotropic polypeptide (GIP), indicating normal intestinal nutrient absorption, or plasminogen activator inhibitor-1 (PAI-1) that is linked to glucose intolerance and inflammation." (PMID 24945157, 2014). "We reviewed the literature on glucose and insulin responses to oral glucose in GIP and GLP-1 receptor KO mice and found that glucose intolerance is not as robustly demonstrated as is generally assumed." (PMID 34122340, 2021).
Glucose intolerance (continued). "There is one published study on GIP in HIV infection, comparing those with versus without glucose intolerance." (PMID 28690913, 2017). "Thus, studies on glucose tolerance after oral glucose administration in GIP and GLP-1 receptor KO mice show a trend but not a general consistency of glucose intolerance." (PMID 34122340, 2021).
metabolic syndrome (22 papers, 2010 to 2025). A cluster of metabolic risk factors for CARDIOVASCULAR DISEASES and TYPE 2 DIABETES MELLITUS. "This study identified an unanticipated efficacy of chronic GIPR agonism to improve dyslipidemia and cardiovascular disease independently of body weight loss, indicating that treatment with acyl-GIP may be a novel approach to alleviate cardiometabolic disease." (PMID 37592302, 2023). "Hence, one can assume that GLP-1/GIP mediated weight loss could actually prime GIP action to improve dyslipidemia." (PMID 37592302, 2023). "Despite concerns about pro-oncogenic effects, dual GIP/GLP-1RAs offer significant potential for mitigating cancer risks in patients with metabolic syndrome." (PMID 40282969, 2025). "The GIP agonist component of tirzepatide may contribute to the findings in most dimensions of metabolic syndrome." (PMID 38341541, 2024). "Acyl-GIP administration resulted in smaller adipocytes within the inguinal fat depot and RNAseq analysis of the latter revealed that acyl-GIP may improve dyslipidemia by directly modulating lipid metabolism in this fat depot." (PMID 37592302, 2023). "Resistin and GIP, regardless of the presence of abdominal obesity, are associated with the presence of renal dysfunction in young people with dyslipidemia." (PMID 37623488, 2023). "Correlation between GIP and PP levels and metabolic syndrome, HRM, pH-impedance parameters." (PMID 31169725, 2019). "Thus, in high GIP subjects, the miR-136 over-expression may lead to dyslipidemia and liver steatosis through suppression of LRH-1 expression." (PMID 32069846, 2020). "Also during catch-up growth in female rats, associated with metabolic syndrome, the administration of (Pro3)GIP reduced visceral fat mass and adipocyte hypertrophy without variations in body weight." (PMID 31447774, 2019). "GIP and GLP-1 have also been proposed as biomarkers for metabolic syndrome and hormonal dysfunction." (PMID 40806228, 2025).
Hepatic steatosis (20 papers, 2014 to 2025). Steatosis is a term used to denote lipid accumulation within hepatocytes. "As GIP acts mainly after meal ingestion, we analyzed some risk factors for the development of fatty liver disease, not only fasting, but also in the postprandial state." (PMID 32069846, 2020). "When combined with GLP-1 or GIP agonism, glucagon receptor agonists may enhance weight loss and metabolic improvements, contributing to greater reductions in liver steatosis and inflammation." (PMID 40590228, 2025). "In addition to biochemical markers, the study attempts to find miRNAs as molecular markers associated with high plasma GIP levels, which may contribute to the risk of fatty liver disease." (PMID 32069846, 2020). "Tirzepatide, a dual agonist (GLP-1/GIP), reduced hepatic steatosis in patients with T2D, demonstrating beneficial effects in the treatment of MASLD." (PMID 41155837, 2025). "GLP-1/GIP dual receptor agonists like tirzepatide have shown potential in improving hepatic steatosis and fibrosis in clinical trials, with particularly significant effects in patients with moderate to severe fibrosis." (PMID 41141254, 2025). "Tirzepatide is a dual glucose-dependent insulinotropic polypeptide (GIP) and GLP-1r agonist that has demonstrated up to 20% body weight loss and improvement in noninvasive hepatic steatosis." (PMID 39928502, 2025). "Differentially expressed microRNAs suggest additional, epigenetic factors, contributing to the development of liver steatosis in patients with impaired GIP signaling." (PMID 32069846, 2020). "Other groups have explored the concept of GLP-1/GIP/glucagon triagonism to obtain extra benefits from adding the benefits of glucagon action (promotion of energy expenditure and amelioration of fatty liver disease) to the ‘twincretin’ effects of GLP-1 and GIP." (PMID 32436022, 2020). "Understanding how enhanced GIP secretion in obese humans can alter plasma miRNA profile and characterizing their target mRNA may help to elucidate potential biological mechanisms for contribution of elevated GIP to the development of liver steatosis." (PMID 32069846, 2020). "Nutrient excess enhances glucose-dependent insulinotropic polypeptide (GIP) secretion, which may in turn contribute to the development of liver steatosis." (PMID 32069846, 2020). "The hypothesis was raised that GIP signaling participates in the development of hepatic steatosis." (PMID 32069846, 2020). "However, our objective was to elucidate how high circulating GIP may influence factors contributing to the development of fatty liver disease." (PMID 32069846, 2020). "This study evaluated the therapeutic effects and molecular mechanisms of tirzepatide, a dual GIP and GLP-1 receptor agonist, in treating hepatic steatosis." (PMID 40837406, 2025). "For example, a high level of glucose-dependent insulinotropic polypeptide (GIP), an intestinal enteroendocrine K cell-secreted hormone, contributes to hepatic steatosis and liver injury by modulating the expression of microRNAs (miRNAs)." (PMID 35002979, 2021). "Preclinical studies also suggest that GIP may synergize with GLP-1 to enhance metabolic control and reduce hepatic steatosis." (PMID 40590228, 2025). "In the research on mice, tirzepatide could improve liver steatosis and inflammation by several mechanisms than vehicle, GLP-1 analog, and GIP analog." (PMID 39610482, 2024). "The reduced glucose-dependent insulinotropic polypeptide (GIP) release observed in WD + WBE mice may be a protective mechanism in terms of reducing adipose tissue storage, hepatic steatosis and glucose homoeostasis." (PMID 29549311, 2018). "Furthermore, treatment with GIP/ICG@P/R8 NPs effectively improves systemic metabolic profiles, including a 9.23% reduction in body weight after 14 days, enhanced insulin sensitivity, and amelioration of fatty liver." (PMID 41256211, 2025).
Hepatic steatosis (continued). "Importantly, the reduced GIP release observed in WD + WBE mice may be a protective mechanism in terms of reducing adipose tissue storage, hepatic steatosis and improving insulin sensitivity." (PMID 29549311, 2018). "As the receptor for GIP (GIPR) is not found to be expressed on hepatocytes, the suggested relation of GIP with fatty liver disease may involve its direct and indirect influence on nutrients’ metabolism, as well as interactions with other endocrine factors regulating liver function." (PMID 32069846, 2020).
heart failure (14 papers, 2021 to 2026). Inability of the heart to pump blood at an adequate rate to meet tissue metabolic requirements. "Our analysis reveals that GLP‐1 and GLP‐1/GIP RAs are associated with reduced risk of composite cardiovascular endpoints and worsening heart failure events." (PMID 41388927, 2025). "Among heart failure patients, elevated Gal-4 levels were associated with higher GIP levels." (PMID 37985679, 2023). "Tirzepatide (TZP), a dual GIP/GLP1-receptor agonist has shown promising results in the SUMMIT trial as improved cardiovascular outcomes in patients with heart failure with preserved ejection fraction (HFpEF)." (PMID 40517248, 2025). "Tirzepatide, a dual GIP/GLP‐1 receptor agonist, offers a novel cardiometabolic strategy beyond glycemic control with important implications for heart failure care." (PMID 41566974, 2026). "In this study, we aimed to investigate the effects of the novel GLP-1/GIP co-agonist tirzepatide and a well-established GLP-1 analogue liraglutide in heart failure." (PMID 40517248, 2025). "For the five outcomes of heart failure (HF), BMI, C-reactive protein (CRP) levels, HDL-cholesterol (HDL-C) and triacylglycerols, there was evidence for Co-localisation also protects at both GIP and GIPR." (PMID 34505161, 2021).
Impaired glucose tolerance (14 papers, 2010 to 2025). An abnormal resistance to glucose, i.e., a reduction in the ability to maintain glucose levels in the blood stream within normal limits following oral or intravenous administration of glucose. "An acute increase in heart rate of ∽5-10 bpm, along with an acute decrease in blood pressure of ∽10–15 mmHg has been shown after GIP infusion in healthy humans, as well as in obese humans with normal or impaired glucose tolerance and T2D." (PMID 40024571, 2025). "In agreement with our in vitro data, GIPA-2 acutely blocked the endogenous GIP incretin effect, impaired glucose tolerance, and inhibited the improved glucose tolerance elicited by exogenously administered native GIP." (PMID 33788878, 2021). "We previously demonstrated that the ability of Xen to amplify the effects of GIP on insulin and glucagon release is greatest in humans with impaired glucose tolerance and therefore, only subjects with impaired glucose tolerance were studied." (PMID 29466430, 2018). "In addition, increased impaired glucose tolerance significantly increased the plasma levels of GIP, GLP-1, and insulin." (PMID 35889886, 2022). "While the role of endogenous GIP signaling in the regulation of blood pressure and heart rate has not been investigated in detail, exogenous GIP has been reported to decrease blood pressure and increase heart rate in individuals with impaired glucose tolerance." (PMID 33240919, 2020). "Xenin infusion also reverses the reduced insulinotropic action of GIP in patients with impaired glucose tolerance but not those with established T2D." (PMID 40024571, 2025). "A TF mixture (25 mg/kg/day) improved impaired glucose tolerance and significantly lower blood glucose levels in prediabetic SDT rats, and increased insulin expression via the inhibition of gastric inhibitory polypeptide (GIP) and glucagon-like peptide-1 (GLP-1) degradation." (PMID 35886943, 2022).
type 1 diabetes (13 papers, 2018 to 2025). "After a 6-day subcutaneous GIP infusion in patients with type 1 diabetes, a 4.6 mmHg reduction in SBP was noted." (PMID 36964557, 2023). "In an islet cell antibody positive group of people, disposed to develop type 1 diabetes, both fasting and postprandial plasma levels of GIP and GLP-1 were normal." (PMID 34294136, 2021). "We and others have described GIP as a dual-acting hormone with both insulinotropic and glucagonotropic effects in isolated human islets, in healthy individuals and in individuals with type 1 diabetes." (PMID 40374968, 2025). "The glucagonotropic effect of GIP at low plasma glucose levels holds promise as a means of reducing the risk of hypoglycaemia in type 1 diabetes, though GIP alone may not be sufficiently effective." (PMID 40374968, 2025). "However, when type 1 diabetes mellitus (T1DM) patients (with low insulin production) were provided a subcutaneous GIP infusion, they showed an increase in NEFA levels during the first 3 h, without changes in fasting plasma levels of C-peptide or insulin." (PMID 38579777, 2024). "In the experiments with treatment alongside cytokine exposure, [d-Ala2]-GIP alone did not prevent the development of the type 1 diabetes phenotype of alpha cells either." (PMID 40374968, 2025). "Similar results were seen in a 24-week study of patients with insulin-treated type 1 diabetes (T1DM), in which the miglitol treated group had a small increase in GLP-1, reduced GIP, needed slightly less exogenous insulin and had fewer pre-prandial hypoglycaemic events." (PMID 29412834, 2018). "Glucose-dependent insulinotropic polypeptide (GIP) dose-dependently increases glucagon secretion under euglycemic and hypoglycemic conditions in healthy individuals and in people with type 1 diabetes (T1D) and T2D, with no direct effect on insulin secretion in healthy individuals." (PMID 40964167, 2025).